SIAH1P1 (siah E3 ubiquitin protein ligase 1 pseudogene 1)
Synonyms: formerly SIAH1L
Gene: Processed pseudogene on chromosome X (35,626,142 to 35,627,064, forward strand). Ensembl gene ENSG00000230227.
Diseases named in the same sentence as SIAH1P1 in open-access papers:
SIAH1P1 is named in the same sentence as 2 diseases in open-access papers, as found by Europe PMC text mining. Sharing a sentence is not in itself a finding about the gene and the disease.
SIAH1P1 shares sentences with these, for which no sentence is quoted: breast carcinoma (1 paper); tumor (1).